Y_RNA (Y RNA )
Gene: Miscellaneous RNA gene on chromosome 5 (31,505,684 to 31,505,788, forward strand). Ensembl gene ENSG00000206682.
Homologues: Orthologues: chimpanzee Y_RNA (99% identical), macaque Y_RNA (93% identical), pig Y_RNA (87% identical), dog Y_RNA (85% identical), guinea pig Y_RNA (72% identical). Paralogues in human: Y_RNA (88% identical), RNY3 (87% identical), Y_RNA (87% identical), Y_RNA (86% identical), RNY3P1 (85% identical), RNY3P14 (85% identical), Y_RNA (85% identical), RNY3P16 (84% identical), Y_RNA (84% identical), Y_RNA (83% identical), Y_RNA (82% identical), RNY3P11 (81% identical), and 93 more.